KDR (kinase insert domain receptor)
Diseases named in the same sentence as KDR in open-access papers (continued):
Sharing a sentence is not in itself a finding about the gene and the disease.
tumor (continued). "Moreover, CREB expression was involved in drug sensitivity to ART And ART/NVB blocked VEGF from interacting with the tumor cell surface receptor KDR and stimulated VEGF/KDR-mediated tumor cell motility, in an autocrine manner." (PMID 31588240, 2019). "Whether there is a difference between EPC subsets in their ability to migrate to GBM tumor tissue remains to be determined (e.g., are KDR+ EPCs better able to home to GBM tissue than other EPCs?" (PMID 31428150, 2019). "In our study, TTAC-0001, a novel fully human anti-VEGFR-2/KDR monoclonal antibody that blocks VEGF/VEGFR-2 signaling, showed selective tumor targeting that lasted at least 6 days, an anti-angiogenic effect to inhibit neovascularization, and anti-tumor efficacy." (PMID 29370209, 2018). "TAL1 is a member of the basic helix-loop-helix family of transcription factors and its downregulation could suppress the activity of the tumor suppressor TGF-β in the early phase of tumor through downregulating KDR expression." (PMID 28178989, 2017). "In this study, we analyzed genotypes of VEGF-A, KDR, Flt4, PDGFRα, HIF-1α and ERCC1 in TETs, aiming to verify whether they correlate with increased tumor risk and/or with the outcome of these patients." (PMID 26254278, 2015). "In particular, KDR is involved in tumor angiogenesis as well as cancer cell growth and survival." (PMID 26325365, 2015). "The response to chemotherapy is associated with tumor angiogenesis, and miR-484 has a potential to improve chemosensitivity through the modulation of tumor angiogenesis, by directly targeting VEGFB and KDR (formerly called VEGFR2)." (PMID 25295252, 2014). "This is consistent with our results, which showed a relatively high loading of KDR on the principal component associated with VEGFC, NRP1, and PLXND1, which had the second highest association with triple-negative (TN) status in the all-tumor data set." (PMID 23667446, 2013). "It is well known that inhibiting of KDR leads to suppression of angiogenesis and tumor growth." (PMID 22408460, 2012). "In addition, Lewis y facilitates the expression of the VEGF receptor, KDR, by autocrine and paracrine pathways, which enhance tumor angiogenesis." (PMID 22138668, 2012). "Therefore, KDR promoter-driven expression of therapeutic genes in tumor vascular endothelial cells can markedly reduce the side effects of gene therapy through targeting the vascular endothelial cells of tumors." (PMID 21333030, 2011). "A substantial body of evidence has emerged suggesting that the axis between the vascular endothelial growth factor (VEGF) receptor and the Flk-1 kinase insert domain receptor (KDR) (VEGF-Flk-1/KDR) is the dominant signal transduction pathway regulating tumor angiogenesis and metastasis." (PMID 22174843, 2011). "We hypothesized that KDR promoter driven double suicide gene could be used as tumor-specific targeting approach to kill the tumor cells." (PMID 21418659, 2011). "That blocking the VEGF-VEGFR-2 pathway may inhibit tumor growth is exemplified in studies using neutralizing KDR/Flk-1 mAb, KDR/Flk-1 kinase inhibitors, or a dominant-negative Flk-1 receptor, all of which were shown to inhibit angiogenesis and tumor growth." (PMID 19545394, 2009). "Targeting two tumour-associated antigens as a mechanism for modulating signalling within the tumour cell to elicit a therapeutic effect was validated by Zu and colleagues using a single-gene bs-diabody molecule specific for VEGFR2 (KDR) and VEGFR3 (Flt-4)." (PMID 18841159, 2008).
tumor (continued). "The anti-tumor effects can be attributed to the antiangiogenic effects of the substance, which are mediated by the inhibition of the receptor tyrosine kinases Flk-1/KDR (VEGR2), PDGFRbeta and FGFR1." (PMID 17367541, 2007). "The highest mean microvessel density (MVD) and the highest VEGF/KDR (vascular endothelial growth factor bound to its receptor on endothelial cells)-activated microvessel density (aMVD) have been shown to be at the invading front of the tumours in NSCLC." (PMID 15328525, 2004). "High expression of both the EC marker KDR/VEGFR2 and the PVC marker CSPG4 showed significant association with poor overall survival (p < 0.05), suggesting that high levels of MCAM gene expression reflect greater vascularisation of tumours and associated poor prognosis." (PMID 37138793, 2023). "However, there is a tumor in the KDR-WT murine group that appears to be an outlier in this group, which could be due to biological variance or technical errors." (PMID 38201446, 2023). "Therefore, the pre-existinganti-cancer activity of high-risk score patients may be limited by high levels of tumor-infiltrating macrophages (M2) and overexpression of many inhibitory immune checkpoints such as TGFBR1 and KDR." (PMID 36090900, 2022). "Moreover, we found that FAK KD HepG2 and Huh-7 cells, but not macroH2A1 KD HepG2 and Huh-7 cells, displayed a simultaneous significant increase (p < 0.01) in the mRNA levels of cancer stemness suppressor genes GATA6, SMAD4, and BMP7, and of tumor-promoting genes KDR and SOX2." (PMID 33182805, 2020). "Finally, the third tumor, #10 (4th resection), did not have any disease associated variants but was found to have a variant of uncertain significance in KDR c.3937G > A p.(D1313N)." (PMID 31046843, 2019). "In addition, EGFR and KDR genes were over-expressed in the tumor tissue." (PMID 29324814, 2018). "Thus, VEGFR-2/KDR holds hope as a target for tumor immunotherapy." (PMID 25502982, 2015). "A common feature observed in many solid tumors, including ccRCC, is the overexpression (oe) of VEGF (vascular endothelial growth factor) and its receptor KDR/VEGFR (kinase insert domain receptor), which play a pivotal role in tumor angiogenesis." (PMID 39477683, 2025). "Researchers have discovered that receptor tyrosine kinases (RTKs), VEGF and its receptor (VEGFR), and VEGFR2 or Flk-1/KDR RTK play key roles in pathological angiogenesis, particularly tumor neovascularization." (PMID 40868085, 2025). "This personalized treatment approach led to a marked reduction in the tumor size within five days and a complete radiologic response within one month, demonstrating the therapeutic value of targeting the VEGF/KDR axis in ONB." (PMID 40710426, 2025). "Research has demonstrated that VEGF initiates and sustains pathological neovascularization, and its inhibition via VEGF receptor 1 (VEGFR-1 and Flt) or VEGF receptor 2 (VEGFR-2, Flk, and KDR) signaling effectively curtails neovascularization and tumor growth." (PMID 40430157, 2025). "Another interesting observation here is the presence of signaling by the VEGF pathway, which involved two upregulated genes (KDR, VEGFA) and three downregulated genes (NRP1, PRKACB, ROCK1) in G2 tumor AOIs compared to G1." (PMID 39245631, 2025).
tumor (continued). "In the high-risk state, the expression levels of VEGFA were significantly increased in Macrophages, Mast cells, Monocytes and tumor cells; FLT1 and KDR were significantly increased in Endothelial; and PGF was significantly increased in Mesangial." (PMID 40563096, 2025). "Our study revealed a correlation between MMP14 expression and various molecules regulating tumor immune cells, including CSF1R, HAVCR2, KDR, PDCD1LG2, TGFB1, CD70, CD86, and CXCL1." (PMID 40352589, 2025). "The majority of DEGs related to this pathway (ITGAV, KDR, VEGFB, AKT1, VEGFA) were downregulated in tumor cells except for HSBP1 and SHC2." (PMID 39245631, 2025). "KDR promotes tumor angiogenesis, while the hypermethylation of the Keap1 promoter reduces KEAP1 expression, contributing to tumor progression." (PMID 40136480, 2025). "For example, we discovered specific highly-expressed pairs KDR-PECAM1, KDR-CDH5, and CD34-SELL between immune cells and malignant tumor cells, thus these genes play an important role for the control of cancers." (PMID 41282090, 2025). "Based on the results obtained, PTGS2, VEGFA, KDR, CXCR1 and CXCR2 were found to be significantly overexpressed in tumour samples compared to paired normal samples." (PMID 38426619, 2024). "Significant upregulation of PTGS2, VEGFA, KDR, CXCR1, and CXCR2 expression were observed in tumour samples compared with paired normal samples." (PMID 38426619, 2024). "Among immunoinhibitors, PVRL2, CD160, KDR and VTCN1 were also negatively correlated with LAMP3 expression in many tumours." (PMID 38146591, 2024). "In our study, we found that PTGS2 and VEGF signalling pathway genes (VEGFA, VEGFB, KDR, CXCR1 and CXCR2) were upregulated in OSCC tumour tissues compared to their paired normal tissues." (PMID 38426619, 2024). "Humanized monoclonal antibodies were developed to inhibit tumor neo-angiogenesis, which is driven by VEGFA/KDR signaling." (PMID 39000466, 2024). "In this study, a significant increase in PTGS2 with VEGFA, KDR, CXCR1 and CXCR2 expression was observed in tumour samples compared to their paired normal samples, with the exception of VEGFB, whose expression was not statistically significant." (PMID 38426619, 2024). "VEGF receptors (KDR, FLT4, FGFR1, and FLT3) and FGF receptors support tumor angiogenesis, providing essential nutrients for growth." (PMID 39273340, 2024). "Cells in IH tumor spheres displayed several stem/progenitor cell markers, including SALL4, kinase insert domain receptor (KDR), and CD133, as well as high amounts of GLUT-1 and vascular endothelial growth factor (VEGF)." (PMID 37149592, 2023). "Here, in correlation with transcriptome data, we demonstrated the detectable protein expression of KDR, FLT4, UNC5A, ADAM12, CD34, and Prox-1 in the human KS tumor microenvironment." (PMID 37046832, 2023). "Angiogenesis is driven by the binding of vascular endothelial growth factor (VEGF), secreted by tumor cells and surrounding stroma, to VEGF receptor 2 (VEGFR2; also known as KDR)." (PMID 37148323, 2023). "In summary, we detected the partial recapitulation of KS tumor microenvironment cell surface protein expression within the xenograft tissues where FLT4, KDR, UNC5A, and ADAM12 mirrored the levels detected in the human KS tumors." (PMID 37046832, 2023). "Previous studies have shown that cediranib is a highly effective VEGFR (KDR) inhibitor and that cediranib targets BRCA2/RAD51 in tumor cells." (PMID 37355516, 2023). "A7R peptide binds to both neuropilin-1 (NRP-1) and vascular endothelial growth factor receptor-2 (VEGFR2/KDR), disrupting their receptor/coreceptor interaction, and impacting, therefore, on angiogenesis and tumor growth." (PMID 37242749, 2023). "FLT1 and KDR are receptors of VEGF, which is the most important factor in promoting angiogenesis in tumours." (PMID 37313656, 2023).
tumor (continued). "We found significantly positive Pearson R values for the majority of tumor entities, especially regarding correlations between FAP and the angiogenesis-related genes FLT1, KDR, HIF1A, and ETS1." (PMID 36672341, 2023). "It was also shown that the expression of the VEGFR-2 gene (KDR) was decreased in the combination group compared to monotherapy in pre- and post-treatment tumor biopsies." (PMID 37999131, 2023). "In retrospective analyses, selected cancer-associated mutations and alterations that are putative targets of sitravatinib in vitro (e.g., RET, MET, CBL, AXL, KDR, and NTRK) were monitored from circulating tumor DNA in baseline plasma samples (n = 49)." (PMID 36842467, 2023). "The two VEGF receptors, KDR and FLT4, are currently being explored for targeted inhibition therapy to reduce immune modulation and immunosuppression in the tumor environment." (PMID 37046832, 2023). "The FLT4, KDR, and UNC5A proteins were detected at high levels within the L1T2 xenografts, mirroring the human KS tumor expression patterns." (PMID 37046832, 2023). "highlights six genes (VEGFA, KDR, ESM1, CD34, PECAM1, and ANGPTL4), but only four of them were expressed by endothelial cells while VEGFA and ANGPTL4 were mainly expressed by tumor cells." (PMID 36423636, 2022). "In CSCC samples, we found an apparent co-localization of VEGF-A, KDR, and Flt-1 in neoplastic keratinocytes of CSCC, suggesting an autocrine positive regulation to promote tumor growth and invasion, as has been postulated before for oral SCC." (PMID 35878392, 2022). "Gliclazide is an anti-diabetic drug inhibiting VEGFA, a known interactor of KDR, and is significantly upregulated in MPM tumour (Log2FC = 1.83, p-value = 0.0018)." (PMID 33916178, 2021). "The expression level of the hub genes KDR and ACTA2 in tumor tissue were compared with their matched normal tissues, and survival curves were plotted." (PMID 34179721, 2021). "Anlotinib was developed by Nanjing Chia Tai Tianqing Pharmaceutical Co., Ltd. as a new oral molecular RTK inhibitor; it targets VEGFR1, VEGFR3, VEGFR2/KDR, PDGFR-α, c-Kit, and FGFRs 1–3 and inhibits TA and tumor cell proliferation." (PMID 34094958, 2021). "The VEGFR2 (fetal liver kinase-1, FLK1, or kinase-insert domain receptor, KDR), belonging to the human VEGF receptor 1-3 family, is over-expressed on tumor vasculatures and is a promising anti-angiogenic target." (PMID 33567640, 2021). "The patients with high KDR, PDGFRA, LRP1, COL1A2, and SAMD9 expression had shorter OS (log-rank test, P < 0.05), indicating that tumor antigens were critical for the progression of diffuse gliomas." (PMID 34815785, 2021). "Another promising target is KDR (VEGFR-2), which is the main mediator of VEGF-induced tumor cell proliferation, migration, survival and increased permeability." (PMID 34987843, 2021). "Among them, VEGF-A and VEGF-C are expressed by the endometrium and VEGF receptor tyrosine kinases, VEGFRs 1 (Flt-1), VEGFR-2 (KDR, Flk-1), and VEGFR-3 (Flt-4), which are exclusively expressed in endothelial cells, hematopoietic stem cells, and tumor cells." (PMID 32637863, 2020). "This compound inhibits miR-21-5p, promotes the expression of TIMP-3, prevents the phosphorylation of KDR and its downstream factor MAPK, and inhibits the proliferation and migration abilities of HUVECs, blocking tumor angiogenesis." (PMID 32762747, 2020).
tumor (continued). "PTIM models of PCB490–3, PCB490–4, and PCB490–5 with integrated RNA-seq data indicated common efficacious mechanisms across the heterogeneous tumor sites: epigenetic modifiers (HDAC, EHMT), PI3K/mTOR inhibition, and VEGF (KDR) signaling inhibition." (PMID 31208434, 2019). "Studies have shown that VEGF‐C and VEGF‐D bind to its receptor VEGFR‐2 (KDR) and receptor VEGFR‐3 (Flt‐4), promoting angiogenesis and/or lymphangiogenesis, thus accelerates tumor growth and metastasis." (PMID 31478352, 2019). "In order to explore the relationship between KDR gene amplification and VEGFR2 expression, we carried out immunohistochemical detection of VEGFR-2 in the resected tumor tissues, and found a moderate degree of expression." (PMID 29855279, 2018). "The VEGFR family includes VEGFR-1(Flt-1), VEGFR-2(KDR/Flk-1), VEGFR-3(Flt-4), NRP-1 and NRP-2 with VEGFR-2 is supposed to be closer to generation of tumor vessels." (PMID 29662638, 2018). "Vascular endothelial growth factor receptor 2 (VEGFR2), also known as kinase insert domain receptor (KDR), is a major mediator of VEGF’s biological effects, and plays a vital role in tumour angiogenesis." (PMID 31070539, 2018). "Considering the fact that other VEGF-like heparin-binding growth factors can prevent specific inhibition of the anti-VEGF antibody in hypoxic tumor microenvironments, targeting VEGFR-2/KDR is more effective for anti-angiogenesis." (PMID 29370209, 2018). "Of these, KDR and FLT1 are both receptors for VEGFA, the predominant mediator of angiogenesis in tumor progression." (PMID 28388297, 2017). "Binding of bevacizumab prevents the interaction of VEGF with its receptors VEGFR-1 (Flt-1) and VEGFR-2 (KDR), and disrupts the formation of new tumor vasculature." (PMID 28134851, 2017). "Significant differences, mirroring the angiogenic patterns, were found in the tumor expression of vascular endothelial growth factor (VEGF) and its receptor VEGFR2 (KDR), which were higher in Delta16 and F1 HER2low/Delta16high tumors." (PMID 28903354, 2017). "This is the case for the kinase KDR (also known as VEGFR2; CAP = 25%), which is targeted by sorafenib and sunitinib to inhibit vascularization of the tumor site." (PMID 29273096, 2017). "Especially, the environment of hypoxia in HCC stimulate tumor cell to secret VEGF,which activates its receptor KDR and result in endothelial cells proliferation, migration and tubal formation." (PMID 28122355, 2017). "The two signal transduction pathways, VEGF/KDR and ANG2/TIE2, play important roles in the process of angiogenesis in tumor growth and metastasis." (PMID 28122355, 2017). "Tumor angiogenesis can be blocked by the miR-200 family members via targeting the VEGF signaling pathway components, such as VEGF-A, FLT1/VEGFR1, and KDR/VEGFR2." (PMID 27240340, 2016). "According to the changes observed in the vasculature, we completed the study with the expression analysis of endothelial-related genes in tumor lysates, such as CD31 (PECAM1), CD34, and VEGFR2 (KDR)." (PMID 27120788, 2016). "KDR (kinase insert domain receptor, also known as VEGFR2) is an important factor in tumor development and progression due to its pro-angiogenic effects." (PMID 26572169, 2015). "NRP1 forms complexes with Flk-1/KDR (VEGFR2) to enhance the binding of VEGF165 to VEGFRs, and promotes VEGF165-mediated tumor angiogenesis, cell migration and tumorigenicity." (PMID 25954957, 2015). "The SCLC group had strongly positive c-Kit in four tumors, EGFR in two, IGF1R in two, and KDR in three, for a total of 10 (16 %) SCLC tumors with a strongly positive RTK (one tumor was strongly positive for both c-Kit and IGF1R)." (PMID 25989941, 2015). "Angiogenesis is a key factor for tumor growth and involves VEGF and the activation of VEGF receptors, Flt1 and KDR." (PMID 26174150, 2015). "These CTLs target tumor vascular endothelial cells that express KDR169-presenting HLA molecules, i.e., VEGFR-2/KDR expressing cells." (PMID 25502982, 2015).